TMSB4Y (thymosin beta 4 Y-linked)
Description:
Plays an important role in the organization of the cytoskeleton. Binds to and sequesters actin monomers (G actin) and therefore inhibits actin polymerization (By similarity).
Synonyms: TB4Y
Tractability: No criterion of Open Targets' tractability assessment is met for any kind of drug.
Gene: Protein-coding gene on chromosome Y (13,703,899 to 13,706,024, forward strand). Ensembl gene ENSG00000154620.
Subcellular location: Cytoplasm, cytoskeleton
Gene Ontology:
Molecular function: protein binding; actin monomer binding; protein sequestering activity
Biological process: regulation of actin polymerization or depolymerization; regulation of cell migration; actin filament organization
Cellular component: cytosol; cytoskeleton
Homologues: Orthologues: chimpanzee TMSB4Y (95% identical), guinea pig TMSB4Y (93% identical), mouse Tmsb4x (93% identical), pig TMSB4X (93% identical), rat Tmsb4x (93% identical), macaque TMSB4Y (84% identical), rabbit TMSB4Y (77% identical). Paralogues in human: TMSB4X (93% identical).
Diseases named in the same sentence as TMSB4Y in open-access papers:
TMSB4Y is named in the same sentence as 11 diseases in open-access papers, as found by Europe PMC text mining. Sharing a sentence is not in itself a finding about the gene and the disease. The quoted sentences say what the papers report.
male breast carcinoma (2 papers, 2015 to 2025). A malignant neoplasm involving the male breast. "These combined data further support that TMSB4Y is a tumor suppressor whose loss contributes to male breast cancer." (PMID 26702755, 2015). "In male breast cancer, TMSB4Y was suggested as a candidate tumor suppressor." (PMID 41431653, 2025).
adenoma (1 paper, 2020). A neoplasm arising from the epithelium. "Several of these genes, e.g., EIF1AY, USP9Y, ZFY, TMSB4Y, have been used as gender-specific tissue biomarkers for both normal and tumoural tissues; corticotrope adenomas can now be added to the list of tissues presenting these markers of sexual dimorphism." (PMID 32183012, 2020).
breast carcinoma (1 paper, 2015). "Taken together, our results show that in situ clonal loss of the human Y chromosome may play an important role in male breast cancer tumorigenesis, and suggest that TMSB4Y has tumor suppressive properties." (PMID 26702755, 2015). "Because male breast cancers are most often ER positive, and MCF-10A are ER negative cells, we wanted to evaluate expression of TMSB4Y in an ER positive breast cancer cell line." (PMID 26702755, 2015).
breast tumor (1 paper, 2015). "We performed immunohistochemistry (IHC) to assess TMSB4Y protein expression in normal male breast tissue, using matched breast tumor tissue with Y loss as a negative control." (PMID 26702755, 2015).
esophageal squamous cell carcinoma (1 paper, 2025). Esophageal squamous cell carcinoma (ESCC) is a type of esophageal carcinoma (EC) that can affect any part of the esophagus, but is usually located in the upper or middle third. "The results of this study very strongly identified the ChrY-encoded, probable tumor suppressor TMSB4Y as a potential prognostic marker in cases of male esophageal squamous cell carcinoma." (PMID 41214505, 2025). "Going further, a study conducted by 2024 directly implicates a ChrY gene, TMSB4Y, in a regulatory cascade which controls the proliferation, invasion, and metastasis of male esophageal squamous cell carcinomas." (PMID 41214505, 2025). "Herein, this group revealed that TMSB4Y contributed to the regulation of sphingomyelin metabolism and, in turn, purine synthesis which ultimately impacted the proliferation of esophageal squamous cell carcinoma cells as well as the growth of xenografted tumors created from them." (PMID 41214505, 2025).
tumor (8 papers, 2015 to 2025). "Regarding the tumor-suppressive genes of the ChrY associated with cancer initiation events, TMSB4Y and KDM5D are the most noteworthy but the UTY gene possesses some tumor suppressive activity as well and is worth mentioning." (PMID 41214505, 2025). "TMSB4Y, which encodes an actin sequestering protein, acts as a candidate tumor suppressor and the overexpression of TMSB4Y results in the change of cell morphology with subsequent retardation of cell cycle progression." (PMID 35120273, 2022). "Expression of the third gene, TMSB4Y, might reduce cell proliferation in tumor cells, suggesting tumor suppressor function." (PMID 27058445, 2016). "Taken together, our results suggest that clonal loss of the Y chromosome may contribute to male breast carcinogenesis, and that the TMSB4Y gene has tumor suppressor properties." (PMID 26702755, 2015). "Functional analysis of TMSB4Y also suggests this gene has tumor suppressor properties." (PMID 26702755, 2015). "Furthermore, the Y chromosome gene TMSB4Y may be a tumor suppressor gene that normally functions through its direct interaction with β-actin, which in turn regulates cell morphology and cell proliferation." (PMID 26702755, 2015). "Furthermore, we found that the expression of TMSB10 in the tumor tissues was the highest among these seven TMSs, and TMSB15A, TMSB4Y and TMSB15B showed relatively low expression." (PMID 36163046, 2022). "To investigate whether TMSB4Y expression is consistent with a tumor suppressor, we sought to determine TMSB4Y expression in normal male breast tissue." (PMID 26702755, 2015).
TMSB4Y also shares sentences with these, for which no sentence is quoted: cancer (2 papers); Alzheimer disease (1); Azoospermia (1); major depressive disorder (1); prostate tumor (1).